FTO (FTO alpha-ketoglutarate dependent dioxygenase)
Diseases named in the same sentence as FTO in open-access papers (continued):
Sharing a sentence is not in itself a finding about the gene and the disease.
Obesity (continued). "There has also been little exploration of whether the fat mass and obesity-associated (FTO) rs9939609 single-nucleotide polymorphism (SNP) is associated with affective symptoms and/or modifies the relationship between BMI and affective symptoms." (PMID 29531329, 2018). "Furthermore, carriers of the AA genotype had a 2.2 point increase in their mean BMI in comparison to those who were carriers of the TT genotype, indicating a strong contribution of FTO on obesity susceptibility." (PMID 29343214, 2018). "Furthermore, neuroimaging studies have demonstrated altered brain reward responses to food stimuli in patients with monogenic forms of obesity and in individuals with common risk alleles of obesity-associated genes (such as FTO and MC4R)." (PMID 28597337, 2018). "Future longitudinal studies will be needed to investigate whether WM microstructural changes in specific regions of the reward network can indeed be regarded as a first step in the development of obesity in carrier of the FTO at-risk allele." (PMID 29520227, 2018). "The FTO gene modulates the activity of the midbrain reward circuitry by regulating the activity of the receptors D2 and D3, providing a potential mechanism for the increased risk for obesity associated to the FTO risk-variants." (PMID 29520227, 2018). "Hence our decision to analyze relationships between particular components of MetS and selected gene polymorphisms, namely peroxisome proliferator-activated receptor gamma (PPAR-γ), fat mass and obesity-associated (FTO), and melanocortin-4 receptor (MC4R)." (PMID 29315078, 2018). "Obesity-related genes, such as FTO, are associated with energy traits." (PMID 30071075, 2018). "Thus, some polymorphism present in genes such as Fat mass and obesity-associated (FTO), Perilipin (PLIN) and β-adrenergic receptor 3 (ADRB3) have been studied associated with obesity development." (PMID 29361938, 2018). "Interestingly, these metabolites were also found to be influenced by the obesity associated variant in the FTO gene during OGTTs." (PMID 28936587, 2018). "FTO locus has been repeatedly reported to be associated with obesity and/or adiposity, and, in this study, we have shown that the risk allele for obesity was significantly associated with susceptibility to diabetic nephropathy in Japanese patients with type 2 diabetes." (PMID 30566433, 2018). "However, genetic epidemiology using Mendelian randomization has also shown an obesity-dependent association between the FTO gene and type 2 diabetes and that the FTO gene predisposes to insulin resistance." (PMID 29274011, 2018). "Moreover, the obesity risk allele of FTO was associated with a lower level of lipolysis in adipocytes, which shows the possible primary role of the FTO gene in adipose tissue." (PMID 29677190, 2018). "FTO is not only statistically the strongest associated gene but also has the largest effect size on obesity risk, yet its physiological role and mechanism of action remain unclear." (PMID 30241328, 2018). "Moreover, the mutations and single nucleotide polymorphisms in theMC4R gene and other genes associated with obesity such as FTO demonstrated the development of obesity caused by PCOS." (PMID 34466430, 2018). "FTO (alpha-ketoglutarate dependent dioxygenase) has been identified as an obesity-associated gene." (PMID 30071075, 2018). "Moreover, obesity risk allele of FTO was associated with the less level of lipolysis in adipocytes that it shows possible primary role of the FTO gene in adipose tissue." (PMID 30126381, 2018). "This significance was degenerative after BMI adjustment, hinting that this FTO polymorphism may exert its influence on OA through obesity." (PMID 29606151, 2018).
Obesity (continued). "The importance of obesity-related factors and oxidative stress in nephropathy risk is also supported by our finding that variants in the FTO and CAT genes, which encode the fat mass and obesity-associated and catalase proteins, respectively, are associated with this diabetic complication." (PMID 29410390, 2018). "Interestingly, in our study the only association found to be significant was in females between FTO rs9939609 and obesity." (PMID 29343214, 2018). "Therefore, the results of this study support the existence of associations between the variants of the FTO gene and obesity." (PMID 30254759, 2018). "It has been postulated that FTO-mediated predisposition to weight gain and obesity may be modified by dietary behaviours." (PMID 29686893, 2018). "Likewise, the benefit of PUFA has been observed for polymorphisms of other genes, such as FTO, and studies have indicated an “anti-obesity” effect from PUFA." (PMID 30126176, 2018). "The top loci in this cluster include the well-known obesity-associated loci FTO and MC4R." (PMID 30240442, 2018). "Multiple single nucleotide polymorphisms (SNPs) occur on the FTO gene that may influence adipogenesis and obesity." (PMID 30124167, 2018). "The FTO SNP (rs1421085) results in a T to C nucleotide substitution that may result in an increased risk for obesity in individuals who carry at least one C allele." (PMID 30124167, 2018). "The rs9939609 SNP (T > A) in FTO gene is associated with obesity and type 2 diabetes." (PMID 29854435, 2018). "In addition, we found the fat mass and obesity-associated protein FTO, an AD risk factor which genetically interacts with APOE, was the most highly connected hub protein of the M1 module." (PMID 29490708, 2018). "The high prevalence of obesity among our diabetic and control group (64 and 44%, respectively) could be attributed to other variants within FTO and or other genes which can be modulated by environmental factors and lifestyle." (PMID 30170548, 2018). "Indeed, a meta-analysis concluded that higher physical activity levels attenuate the influence of FTO variation on obesity risk by 30%, and exercise interventions have demonstrated efficacy in promoting weight loss in FTO risk allele carriers." (PMID 29686893, 2018). "In addition to leptin signaling, overlap with several genes implicated in body mass index was found, including fat mass and obesity–associated gene (FTO), SEC16B, TMEM18, and NEGR1." (PMID 29161441, 2018). "According to the results of several studies, the individuals at high risk for obesity development may be homozygous for both FTO and MC4R genes or may be homozygous for one of the two genes and heterozygous for the other." (PMID 30338250, 2018). "In addition, the authors also identified that both MC4R and FTO risk genotypes increase the metabolic risk in children with obesity." (PMID 30338250, 2018). "However, that study revealed a significant correlation between LDL and FTO rs9939609 supporting the idea that this variant can be a determinant of obesity due to its effect on the lipid profile." (PMID 30170548, 2018). "The FTO polymorphism (rs8044769) might exert its effect on osteoarthritis through obesity, because it was reported as a body mass index-associated single-nucleotide polymorphism." (PMID 29606151, 2018). "Many polymorphisms of the FTO gene are studied for the possible association with obesity." (PMID 30126381, 2018). "Many polymorphisms of the FTO gene were studied for the possible association with obesity." (PMID 29677190, 2018). "Our observations highlight the necessity, and challenge to reveal the genetic basis of obesity complex trait in population of Poles but also give a novel point of view for FTO genetic association with overweight and obesity as a more complex and not yet well-known issue." (PMID 28662178, 2017).
Obesity (continued). "The haplotype analysis exhibited that the strongest obesity associated haplotype (χ2 = 11.474, p = 0.0007) which contained the minor alleles for SNPs distributed across a 45-kb stretch of intron 1 of FTO, was in block 8 and occurred at a frequency of 0.46 in the case group and 0.41 in controls." (PMID 28662178, 2017). "Very recently, it was shown that genetic variants within FTO gene are linked functionally to another distant gene called IRX3 which may link the association of FTO SNPs with both obesity and T2DM." (PMID 28915859, 2017). "In order to understand how FTO may be associated with TL it is important to consider the role of the FTO gene in the context of its function, regulation and obesity." (PMID 28859657, 2017). "Also, two Single Nucleotides polymorphism (SNPs) are associated with T2DM risk: transcription factor 7-like 2 (TCF7L2) and fat mass and obesity-associated (FTO) gene on chromosome 16." (PMID 27894098, 2017). "As obesity is a well established risk factor for most types of cancer, it is interesting and important to investigate whether FTO SNPs are associated with risk of cancer." (PMID 28881622, 2017). "Few studies have examined the interaction of dietary factors (e.g., fiber intake) and FTO-genetic predisposition or genetic structure on the risk of obesity in a Middle-Eastern population, and most studies to date pertain to interactions between FTO and dietary macronutrients." (PMID 29273742, 2017). "The molecular basis of the association between the FTO locus and obesity have been hypothesized, even though the involved cell types and target genes remain uncharacterized." (PMID 28282466, 2017). "Genetic variations in the FTO locus are associated with obesity." (PMID 29053636, 2017). "It has been suggested that the obesity-associated FTO SNPs may affect obesity through greater food intake and increased hunger/lowered satiety and through modulating adiposity factors." (PMID 28507607, 2017). "The first intronic FTO variant rs9939609 was selected specifically in this study as it depicted the highest genotyping success rate among other obesity risk SNPs and has strong genome wide association evidence with obesity." (PMID 28915859, 2017). "Soon after the finding that FTO variation affects obesity risk, data emerged from two epidemiological studies showing that FTO variation may modify the relationship between physical activity and estimates of adiposity in European and North American adults." (PMID 28124081, 2017). "Notably, single nucleotide polymorphisms of FTO, which are associated with increased FTO expression increase the risk for obesity and T2DM." (PMID 28933365, 2017). "Additionally, nutrition interventions for preventing or treatment of obesity need to be promoted and targeted according to subgroups with FTO or other SNP risk alleles." (PMID 28954439, 2017). "Previous studies suggested that genetic association to obesity at the FTO locus may be age dependent." (PMID 28662178, 2017). "Furthermore, expression of 11beta-hydroxysteroid dehydrogenase type 1 (11β-HSD1) and fat mass and obesity associated gene (FTO), were also significantly depressed." (PMID 29152131, 2017). "The fat mass and obesity-associated (FTO) gene is located on chromosome 16 (16 q12." (PMID 28208657, 2017). "For other cardiometabolic traits, the obesity predisposing locus, FTO-rs1558902 yielded significant association with systolic blood pressure (SBP) (P = 0.001), while the risk alleles of SNPs in/near GNPDA2, PCSK1 and MAP2K5 yielded nominal association with blood pressures (P < 0.05)." (PMID 29212175, 2017). "However, a meta-analysis did not support the interaction between total energy or macro-nutrient intakes and the FTO genetic variant of rs9939609 in relation to obesity." (PMID 28954439, 2017). "This is similar to other studies that showed that PA might mitigate the effects of gene variant FTO rs9939609 on obesity." (PMID 28607773, 2017).
Obesity (continued). "Genetic variants of FTO were the first common genetic variants to be associated with increased obesity and BMI, with 89 genetic variants in introns 1 and 2 that have the strongest genome-wide association signal and are in high linkage disequilibrium in Europeans." (PMID 28615046, 2017). "In particular, high-risk variant in FTO could affect eating behaviours (i.e. by means of binge-eating episodes) and promote excessive weight gain and obesity." (PMID 28282466, 2017). "We thus analyzed whether the functional private ABCA1-R230C risk allele might interact with the most replicated obesity risk allele FTO rs9939609." (PMID 28464932, 2017). "Consequently, FTO single-nucleotide polymorphisms (SNPs) increase the risk of obesity by 1.20–1.32 fold in Europeans6 and by 1.25 fold in Asians7." (PMID 29273742, 2017). "Of these, fat mass and the obesity-associated gene (FTO) locus was found to be consistently associated with obesity traits in several populations, which could increase body mass index (BMI) by 0.22–0.66 per risk allele." (PMID 28954439, 2017). "Impact of obesity predisposing variants of FTO on BMI changes throughout life." (PMID 28662178, 2017). "Rs9939609 is a common polymorphism of FTO gene and has been identified to link with obesity." (PMID 28451524, 2017). "Interestingly, polymorphisms in FTO were significantly associated with susceptibility to MS and obesity, higher BMI, lower HDL concentrations, and higher SBP in our control group." (PMID 28738793, 2017). "Finally, SNPs in FTO were found to be significantly associated with BMI and susceptibility to obesity in the general unmatched control group." (PMID 28738793, 2017). "Except for obesity and race, metabolic syndrome may be another important factor influencing the association between FTO polymorphism and PCOS." (PMID 28451524, 2017). "Thus, within different FTO variants, those alleles that have been positively associated with obesity-related phenotypes are referred to as risk alleles, while those negatively associated with such traits are referred to as protective alleles." (PMID 28103813, 2017). "In 2007 three independent studies identified FTO as obesity susceptibility gene." (PMID 28662178, 2017). "These INDELs and VNTRs could be found in the obesity loci or genes from the earliest GWAS and candidate gene association studies, like FTO, genes in the leptin–proopiomelanocortin pathway, and UCP2/3." (PMID 28615046, 2017). "This might propose a mechanism of understanding of FTO-linked weight gain and obesity in the Nigerian context, but further study with larger sample size and objective measures of environmental variable is warranted." (PMID 28607773, 2017). "While we replicate the interaction with PA for the strongest known obesity-risk locus in the FTO gene, of which the effect is attenuated by ~30% in physically active individuals compared to inactive individuals, we do not identify additional loci that are sensitive to PA." (PMID 28448500, 2017). "The FTO rs9939609 SNP is the most commonly reported population obesity gene in association studies." (PMID 28859657, 2017). "Additionally, rs7206790 in the obesity-associated FTO gene was among the top SNPs for EPA+DHA intake: the body mass index-raising G allele was associated with 7mg/day greater EPA+DHA intake (P = 7.44x10-7)." (PMID 29236708, 2017). "Fat mass and obesity-associated (FTO) gene influences obesity but studies have shown that environmental/lifestyle variables like physical activity (PA), time spent sitting (TSS), and energy intake might mediate the effect." (PMID 28607773, 2017). "Variants in the FTO locus are reported to be one of the strongest genetic predictors of obesity." (PMID 28662178, 2017).
Obesity (continued). "Authors analyzed the genetic variants that cause lifelong high BMI in FTO (fat mass and obesity-associated gene, rs9939609), MC4R (Melanocortin-4 Receptor gene, rs17782313) and TMEM18 (transmembrane protein 18, rs6548238) genes to evaluate the consequences of the obesity in COPD patients." (PMID 28335527, 2017). "Furthermore, polymorphisms in the FTO gene were associated with increased obesity risk, whereas polymorphisms in the FTO and FABP2 genes were also associated with the risk of developing MS in general unmatched cohorts." (PMID 28738793, 2017). "Some FTO variants already associated with obesity are also associated with CAD risk factors." (PMID 26878843, 2016). "The association of FTO with obesity is strongly replicable in most populations." (PMID 26726774, 2016). "Recently, MEFs have been used to study adipogenesis in vitro as well as mechanisms related to obesity such as genes or transcription factor implicated in the adipogenesis process, signaling pathways in adipocytes, or the known fat mass and obesity-associated (FTO) gene." (PMID 27376273, 2016). "However, the majority of common obesity in humans is polygenic, with the most reproducible finding from genome-wide association studies, an association at the fat mass and obesity (FTO) locus, explaining only a small component of obesity risk." (PMID 27157046, 2016). "In this study, we examined whether dietary factors and physical activity modified the association between two FTO single nucleotide polymorphisms (rs8050136 and rs11076023) (SNPs) and obesity traits and type 2 diabetes (T2D)." (PMID 27274759, 2016). "The strongest of these, FTO, was the first GWAS-identified susceptibility gene for common obesity." (PMID 27846319, 2016). "FTO was the first gene to be associated with obesity by genome-wideassociation studies (GWAs)." (PMID 27560839, 2016). "Genetic studies have shown that obesity risk is heritable and that, of the many common variants now associated with body mass index, those in an intron of the fat mass and obesity-associated (FTO) gene have the largest effect." (PMID 27596730, 2016). "Approximately 16% of the general population is homozygous for the common FTO rs9939609 risk variant (AA), and the odds of obesity among this group are approximately 70% higher for adults and children >7 years old compared to those who are homozygous for the wild type variant (TT)." (PMID 27196523, 2016). "The fat mass and obesity associated (FTO) gene plays an important role in adipogenesis." (PMID 26964098, 2016). "If FTO variants confer obesity risk by driving the expression of IRX3, one may expect increased expression of IRX genes in obese subjects." (PMID 27560134, 2016). "The fat mass and obesity-associated protein FTO is overexpressed in MA cells." (PMID 27390851, 2016). "Our data suggest that regular PA may modify the effect of FTO genetic contribution to the obesity risk including BMI, fat mass, and hip circumference." (PMID 26908368, 2016). "Continuous efforts have been conducted to further clarify the functional role of FTO and it seems that previous work may reasonably support the mechanism underlying the link between FTO genetic variants and obesity." (PMID 26908368, 2016). "In contrast, SNPs near KCNQ1 and in FTO were associated with obese T2D and mediated via obesity." (PMID 27281091, 2016). "In addition, a growing number of studies have reported that physical inactivity confers an increased risk of FTO genetic predisposition to obesity while physically active participants who have risk allele(s) of FTO SNPs exhibited lower risk for obesity." (PMID 26908368, 2016). "The potential functional link between FTO and IRX3 is supported by evidence from murine, human, and in vitro studies showing that the IRX3 promoter strongly interacts with the obesity-associated interval within FTO, and that obesity-linked SNPs are associated with IRX3 but not with FTO expression." (PMID 27560134, 2016).